FH (fumarate hydratase)
Diseases named in the same sentence as FH in open-access papers (continued):
Sharing a sentence is not in itself a finding about the gene and the disease.
hereditary leiomyomatosis and renal cell cancer (continued). "For example, germline mutations of FH, which lead to a metabolic shift to aerobic glycolysis, are associated with the development of the genetic syndrome of hereditary leiomyomatosis and renal cell cancer (HLRCC), which is characterized by an aggressive papillary type II renal cell carcinoma." (PMID 25859550, 2015). "Heterozygous mutations in the encoding FH gene cause hereditary leiomyomatosis and renal cell cancer (HLRCC) syndrome characterized by multiple cutaneous leiomyomas, benign smooth muscle tumors of the uterus, aggressive renal cell carcinomas, and testicular cancer." (PMID 25126540, 2014). "Both fumarate and succinate reach very high levels in hereditary cancers associated with the inactivation of fumarate hydratase (FH, hereditary leiomyomatosis and papillary renal cell carcinoma) and succinate dehydrogenase (SDH, hereditary paraganglioma) respectively." (PMID 24491179, 2014). "Furthermore, heterozygous germline mutations in fumarate hydratase (FH) can cause a rare disorder of hereditary leiomyomatosis and renal cell carcinoma (HLRCC [MIM 150800])." (PMID 22428002, 2012). "PBMAH may also result from alterations in MC2R, PRKACA, and phosphodiesterase (PDE)11A genes, and it can occur as part of familial tumor syndromes such as McCune-Albright syndrome (GNAS), MEN1, familial APC, or hereditary leiomyomatosis and renal cell carcinoma (FH gene variant)." (PMID 41503047, 2026). "Hereditary leiomyomatosis and renal cell cancer (HLRCC) is an autosomal dominant condition caused by heterozygous mutations in the fumarate hydratase (FH) gene." (PMID 41331641, 2025). "Importantly, heterozygous germline variants in FH confer susceptibility to hereditary leiomyomatosis and renal cell cancer (HLRCC), a rare autosomal dominant condition characterized by early-onset cutaneous and uterine leiomyomas as well as renal cysts and tumors." (PMID 41300720, 2025). "Moreover, germline mutations in the fumarate hydratase (FH) gene that predispose to hereditary leiomyomatosis (a benign tumor of smooth muscle origin) and renal cell cancer (HLRCC) cause a buildup of fumarate that leads to the formation of succinic GSH, a covalent conjugate between fumarate and GSH." (PMID 39061841, 2024). "The accumulation of fumarate due to loss-of-function mutations at the FH encoding gene causes the development of hereditary leiomyomatosis and renal cell cancer (HLRCC)." (PMID 39201738, 2024). "FH mutations increase the risk of developing the autosomal dominant syndrome, hereditary leiomyomatosis and renal cell cancer (HLRCC)." (PMID 37663422, 2023). "Hereditary leiomyomatosis and renal cell cancer (HLRCC) is a rare autosomal dominant genetic disorder resulting from mutations in the fumarate hydratase (FH) gene." (PMID 38098923, 2023). "Fumarase also acts as a tumour suppressor, and FH mutations in humans are commonly found in hereditary leiomyomatosis and renal cell cancer (HLRCC), a cancer syndrome characterized by a malignant form of renal cancer." (PMID 35382567, 2022). "FH inactivating mutations can cause hereditary leiomyomatosis and renal cell cancer (HLRCC), a hereditary cancer syndrome that follows an autosomal dominant inheritance pattern with incomplete penetrance." (PMID 35320498, 2022). "Hereditary leiomyomatosis and renal cell cancer (HLRCC) is now linked to a germline mutation in the fumarate hydratase (FH) gene that encodes a Krebs cycle enzyme, transforming fumarate to malate." (PMID 36118792, 2022). "Hereditary leiomyomatosis and renal cell cancer (HLRCC) is a rare autosomal dominant disorder that results from a germline mutation in the fumarate hydratase (FH) gene; it manifests as cutaneous leiomyomas, uterine fibroids, and renal cell cancer (RCC)." (PMID 34722283, 2021). "FH inactivation was proved to predispose individuals to hereditary leiomyomatosis and renal cell cancer (HLRCC)." (PMID 33777960, 2021).
hereditary leiomyomatosis and renal cell cancer (continued). "Pathogenic mutations in fumarate hydratase (FH) drive hereditary leiomyomatosis and renal cell cancer (HLRCC) and increase the risk of developing uterine leiomyomas (ULMs)." (PMID 33931688, 2021). "Papillary type 2 is the most common histological subtype of RCC that occurs in hereditary leiomyomatosis and renal cell cancer (HLRCC) a condition in which the fumarate hydratase (FH) gene is mutated." (PMID 33650834, 2021). "Loss of function of fumarate hydratase (FH) was linked to overproduction of fumarate, and gave rise to hereditary leiomyomatosis and renal cell cancer (HLRCC)." (PMID 32799884, 2020). "Apart from epigenetic alterations, increased fumarate upon FH loss in hereditary leiomyomatosis and renal cell cancer (HLRCC) modulated NFE2-related factor 2, which promoted EMT via activation of NOTCH1." (PMID 32839493, 2020). "Hereditary leiomyomatosis and renal cell cancer (HLRCC) is an autosomal dominant cancer predisposition syndrome caused by heterozygous germline pathogenic variants in the fumarate hydratase (FH; OMIM*136850) gene." (PMID 32463173, 2020). "Hereditary leiomyomatosis and renal cell cancer syndrome (HLRCC), caused by heterozygous germline pathogenic variants in the FH, confers an increased risk for cutaneous and uterine leiomyomas and renal cancer." (PMID 32463173, 2020). "Leiomyomas with FH deficiency constitutes a rare but clinically relevant subtype, as pathogenic germline variants in FH predispose to hereditary leiomyomatosis and renal cell cancer (HLRCC)." (PMID 33352722, 2020). "Hereditary Leiomyomatosis and Renal Cell Cancer (HLRCC) is an autosomal dominant syndrome caused by heterozygous pathogenic germline variants in the fumarate hydratase (FH) gene." (PMID 31792767, 2020). "FH loss leads to hereditary leiomyomatosis and renal cell cancer (HLRCC), a cancer syndrome characterised by benign smooth muscle tumours in the skin and uterus, and type II papillary renal cancer." (PMID 30190474, 2018). "Inactivating germline mutations in FH cause hereditary leiomyomatosis and renal cell cancer (HLRCC), a cancer syndrome characterised by accumulation of fumarate." (PMID 30190474, 2018). "An excess of fumarate is well-described in tumors and may be linked to germline mutations in fumarate hydratase (FH), a condition which predisposes to hereditary leiomyomatosis and renal cell cancer, but interestingly also evidences for a link with FH are reported in breast and bladder carcinomas." (PMID 29434411, 2017). "Fumarate hydratase (FH) catalyzes the hydration of fumarate into malate and FH germline mutations are implicated in hereditary leiomyomatosis and renal cell cancer (HLRCC)." (PMID 29257069, 2017). "Soon after this seminal discovery, fumarate hydratase (FH), the enzyme that converts fumarate to malate, was found mutated in hereditary leiomyomatosis and renal cell cancer (HLRCC)." (PMID 26130389, 2015). "Mutations in fumarate hydratase (FH) on chromosome 1q43 cause a rare cancer syndrome, hereditary leiomyomatosis and renal cell cancer (HLRCC), but are rare in nonsyndromic and common uterine leiomyoma (UL) or fibroids." (PMID 26113603, 2015). "Further, the GEM analysis was applied to hereditary leiomyomatosis and renal cell cancer (HLRCC) to unravel the survival mechanism that enables the HLRCC cells to operate the mitochondrial electron transport chain despite mutations on FH." (PMID 25232952, 2014). "Germline mutations of FH were originally discovered in hereditary leiomyomatosis and renal cell cancer (HLRCC)." (PMID 25057353, 2014). "The finding that FH-deficient cells become auxotrophic for arginine opens a new therapeutic perspective for the cure of hereditary leiomyomatosis and renal cell cancer (HLRCC)." (PMID 24280230, 2013). "Germline mutations of FH are associated with an inherited form of renal cancer referred to as Hereditary Leiomyomatosis and Renal Cell Cancer (HLRCC)." (PMID 21695080, 2011).
hereditary leiomyomatosis and renal cell cancer (continued). "FH‐deficient renal cell carcinoma (FH‐deficient RCC), previously referred to as hereditary leiomyomatosis and renal cell carcinoma (HLRCC) syndrome‐associated RCC, is a distinct subtype of RCC, characterized by biallelic inactivation of the FH gene." (PMID 41384711, 2026). "Hereditary Leiomyomatosis and Renal Cell Carcinoma (HLRCC): FH inactivation causes fumarate accumulation, protein succination, and GPX4 dysfunction." (PMID 41425591, 2025). "Metabolic gene mutations, such as those in fumarate hydratase (FH) and succinate dehydrogenase (SDH), underlie aggressive RCC variants like hereditary leiomyomatosis RCC." (PMID 40565559, 2025). "Germline mutations in the FH gene that deactivate the enzyme and thus alter TCA functioning can cause hereditary leiomyomatosis and renal cell carcinoma (HLRCC)." (PMID 40956032, 2025). "Hereditary leiomyomatosis and renal cell cancer (HLRCC; OMIN #150800) is a rare autosomal-dominant disorder caused by a heterozygous germline mutation in the fumarate hydratase (FH) gene, which encodes an enzyme that is part of the tricarboxylic acid cycle." (PMID 39184870, 2024). "Therefore, the term 'hereditary leiomyomatosis and renal cell cancer' (HLRCC) has been replaced by 'FH-deficient renal cell carcinoma' in the WHO 2022 classification." (PMID 38765391, 2024). "Conventional fumarate hydratase-deficient renal cell carcinoma (FH-deficient RCC) is usually considered a high-grade, aggressive subtype of RCC that is frequently seen in the hereditary leiomyomatosis renal cell carcinoma (HLRCC)." (PMID 39659780, 2024). "Germline mutations of FH are associated with Multiple Cutaneous Leiomyomas with Uterine Leiomyomas (MCUL) syndrome, also known as Reed syndrome, and share features with hereditary leiomyomatosis and renal cancer cell (HLRCC)." (PMID 37601653, 2023). "Hereditary leiomyomatosis and renal cell cancer (HLRCC) are hereditary cancer syndromes characterized by the inactivation of FH." (PMID 37580393, 2023). "FH-deficient RCC is a renal tumor newly defined by the WHO (5th edition) in 2022 and was named hereditary leiomyomatosis renal cell carcinoma (HLRCC)-associated RCC by the WHO (4th edition) in 2016." (PMID 37076922, 2023). "Hereditary leiomyomatosis and renal cell cancer (HLRCC) is familial cancer syndrome associated with an aggressive RCC type, which is caused by germline FH mutation." (PMID 36359359, 2022). "Fumarase deficiency (also known as fumaric aciduria) is a rare, life-limiting,autosomal recessive disorder associated with encephalopathy, hypotonia and seizures.Heterozygous germline mutations of FH are associated withhereditary leiomyomatosis and renal cell cancer (HLRCC)." (PMID 34841955, 2022). "Pathogenic FH mutations may also be inherited, causing Hereditary Leiomyomatosis and Renal Cell Cancer (HLRCC)." (PMID 36068196, 2022). "Genetic alterations of the fumarate hydratase gene (HF) have been frequently displayed in a rare hereditary form of type 2 pRCC, described among patients affected by hereditary leiomyomatosis RCC (HLRCC)." (PMID 34207825, 2021). "In hereditary leiomyomatosis and renal cell carcinoma (HLRCC) (which is an aggressive form of type 2 PRCC), mutation of Fumarate Hydratase (FH) located on chromosome 1 is relatively common." (PMID 34358255, 2021). "Hereditary leiomyomatosis and renal cell carcinoma (HLRCC), is an uncommon autosomal-dominant disease caused by mutations of fumarate hydratase (FH) gene." (PMID 34889279, 2021). "Mutations of FH gene are associated with hereditary leiomyomatosis, “fumarate hydratase deficient renal cell cancer (RCC)” (“FH-deficient RCC”) and in a very few cases with PPGL." (PMID 34439371, 2021).
hereditary leiomyomatosis and renal cell cancer (continued). "Studies have reported that FH plays an important role in hereditary leiomyomatosis and renal cell cancer (HLRCC)." (PMID 34737838, 2021). "Fumarate hydratase (FH) is an enzyme in the tricarboxylic acid (TCA) cycle, biallelic loss-of-function mutations of which are associated with hereditary leiomyomatosis and renal cell cancer." (PMID 32747645, 2020). "For example, in hereditary leiomyomatosis and renal cell cancer (HLRCC), a high level of fumarate caused by genetic mutation of fumarate hydratase induces the succination of Kelch-like ECH-associated protein 1 (KEAP1) accompanied by the consumption of a fumarate molecule." (PMID 32943735, 2020). "Similarly, loss-of-function FH mutations lead to hereditary leiomyomatosis and renal cell cancer (HLRCC), paragangliomas and pheochromocytomas." (PMID 31277295, 2019). "Erastin efficiently kills also hereditary leiomyomatosis and renal cell cancer cells characterized by inactivation of the enzyme fumarate hydratase (FH), through induction of ferroptosis." (PMID 31426306, 2019). "FH-deficient RCC and hereditary leiomyomatosis and renal cell carcinoma associated RCC have been discussed extensively in the recent literature." (PMID 31905821, 2019). "Hereditary leiomyomatosis and renal cell carcinoma (HLRCC) is characterized by germline mutations of the FH gene that encodes for the TCA cycle enzyme, fumarate hydratase." (PMID 31804603, 2019). "One minor but aggressive subtype of RCC has been recently identified: hereditary leiomyomatosis and renal cell cancer (HLRCC), which bears morphological similarities to high-grade pRCC and is characterized by germline mutations of the Fumarate Hydratase (FH) gene." (PMID 31336988, 2019). "A study by Xie et al63 on hereditary leiomyomatosis and renal cell carcinoma (HLRCC) syndromes reported that fumarase (FH)‐deficient cells had a strong invasive potential, while inhibition of LDHA activity inhibits the mobility of cells." (PMID 30403008, 2018). "The most striking UL predisposing condition thus far characterized is hereditary leiomyomatosis and renal cell cancer (HLRCC) syndrome, caused by high-penetrance germline mutations in the Fumarate hydratase (FH) gene." (PMID 30226466, 2018). "FH is also a tumor suppressor, mutated in hereditary leiomyomatosis and renal cell cancer (HLRCC)." (PMID 28954230, 2017). "The hereditary leiomyomatosis and renal cell cancer (HLRCC) association is a rare syndrome caused by mutation of the Kreb's cycle enzyme, fumarate hydratase (FH)." (PMID 26380143, 2015). "The biallelic inactivation of FH leads to hereditary leiomyomatosis and renal cell cancer (HLRCC), a hereditary cancer syndrome characterized by the presence of benign tumours of the skin and uterus, and a highly malignant form of renal cell cancer." (PMID 25613188, 2015). "The familial leiomyomatosis and RCC syndrome have been correlated with mutations in the fumarate hydratase gene (FH) and patients present with type 2 papillary RCC." (PMID 25274276, 2014). "Germ line met proto-oncogene (MET) and FH alterations are observed in the hereditary form of papillary 1 and in the hereditary leiomyomatosis (type 2), respectively." (PMID 25274276, 2014). "In hereditary leiomyomatosis and renal cell cancer (HLRCC), the loss of the TCA cycle enzyme fumarate hydratase (FH) leads to accumulation of the metabolite fumarate and renal cell cancer." (PMID 25671107, 2014). "Fumarate hydratase (FH) has been identified as a tumor suppressor because germline loss-of-function mutations are associated with the development of hereditary leiomyomatosis and renal cell cancer (HLRCC)." (PMID 23499446, 2013). "Early studies of two familial cancer syndromes, the multiple cutaneous and uterine leiomyomatosis (MCUL1), and the hereditary leiomyomatosis and renal cell cancer (HLRCC), implicated FH, a gene on chromosome 1q43 encoding the tricarboxylic acid cycle fumarate hydratase enzyme." (PMID 23555580, 2013).
hereditary leiomyomatosis and renal cell cancer (continued). "Many lines of evidence have indicated a strong genetic component to hereditary leiomyomatosis and renal cell cancer (HLRCC), and mutation of fumarate hydratase (FH) at 1q43 has been found to cause this condition." (PMID 23203078, 2012). "FH-deficient uterine leiomyomas represent a distinct variant occurring sporadically or in the setting of hereditary leiomyomatosis and renal cell carcinoma (HLRCC), caused by inactivating FH mutations that lead to loss of enzyme activity and fumarate accumulation." (PMID 41463261, 2025). "Similarly, high-grade papillary or eosinophilic tumors with bizarre nuclei should be evaluated for FH loss and 2-succinyl-cysteine (2SC) accumulation to diagnose FH-deficient RCC, a hereditary leiomyomatosis-associated variant." (PMID 41426798, 2025). "The AVATAR trial, a phase II clinical trial, included patients with hereditary leiomyomatosis and papillary RCC, a familial cancer syndrome caused by an enzyme FH mutation, versus patients with sporadic papillary RCC and at most two previous treatments with VEGFR inhibitor agents." (PMID 38594593, 2024). "The first patient, who was not tested for MiT-RCC, showed an FH mutation in the context of a hereditary leiomyomatosis and RCC cancer syndrome." (PMID 36900194, 2023). "Finally, iMFA was used to analyze the impact of loss-of-function mutations in fumarate hydratase (FH), a TCA cycle enzyme associated with hereditary leiomyomatosis and renal cell cancer." (PMID 36355149, 2022). "Fumarate hydratase–deficient renal cell carcinoma (fhRCC) is characterized by loss of the FH gene and was first identified as part of the inherited disease hereditary leiomyomatosis and renal cell cancer (HLRCC) in which patients have a germline loss of FH function." (PMID 35438388, 2022). "Whilst homozygous FH mutations cause fumaric aciduria, a condition associated with infantile encephalopathy and brain malformations, heterozygous FH mutations followed by the loss of heterozygosity of the second allele cause Hereditary Leiomyomatosis and Renal Cell Cancer (HLRCC)." (PMID 27117029, 2016). "Likewise, mutations in fumarate hydratase (FH) and succinate dehydrogenase (SDH) subunits, which are associated with hereditary leiomyomatosis and RCC (HLRCC) and hereditary paraganglioma–pheochromocytoma syndrome, respectively, also induce metabolic perturbations and HIF stabilization." (PMID 39807625, 2025). "Mutations in the FH gene, encoding human fumarase, are associated with fumarate hydratase deficiency (FHD) and hereditary leiomyomatosis and renal cell cancer (HLRCC)." (PMID 29456767, 2018). "Based on the current nomenclature, autosomal dominant Hereditary Leiomyomatosis and Renal Cell Cancer (HLRCC, MIM150800) describes the exact cancer syndrome with germline heterozygous variant of the FH gene, which encodes fumarate hydratase, an enzyme in the Krebs cycle." (PMID 40264827, 2025). "In addition, the Krebs cycle enzyme fumarate hydratase deprivation (FH-/-) demonstrated synergy with ferroptosis inducers for the limiting of hereditary leiomyomatosis and renal cell cancer (HLRCC) progression." (PMID 37325669, 2023). "In hereditary leiomyomatosis and renal cell cancer (HLRCC), the inactivation of fumarate hydratase (FH) leads to the accumulation of much fumarate." (PMID 37739961, 2023). "Inactivating mutations in SDH and FH have been associated with cancers including paraganglioma/pheochromocytomas (PPGL) and hereditary leiomyomatosis and renal cell cancer (HLRCC), amongst others, and lead to elevated levels of succinate and fumarate, respectively." (PMID 32985654, 2020). "Type II papillary kidney cancer has been described in literature along with “hereditary leiomyomatosis renal cell carcinoma (HLRCC),” which also has its characteristic gene – the fumarate hydratase coding gene." (PMID 25120953, 2014).